DNMT3B (DNA methyltransferase 3 beta)
Diseases named in the same sentence as DNMT3B in open-access papers (continued):
Sharing a sentence is not in itself a finding about the gene and the disease.
breast carcinoma (continued). "This unbiased approach allowed us to identify a panel of five biomarkers, DNMT3B, EXO1, MCM10, CENPF and CENPE, that are robustly and significantly associated with disease-free survival prognosis in breast cancer." (PMID 37592220, 2023). "In our study, we found decreased HDAC2 and HDAC8 expression, inhibited HDACs activity, decreased DNMT3b expression, and decreased DNMTs activity, indicating that inulin dietary treatment induced protective epigenetic changes in mammary tumor cells in mice." (PMID 37240357, 2023). "Next, ROC curve analysis for DNMT3B and ALYREF revealed their significant diagnostic roles in breast cancer." (PMID 35812757, 2022). "DNMT3B overexpression is responsible for hypermethylation phenotype in multiple breast cancer cell lines." (PMID 35620052, 2022). "ROC curve analysis was conducted to determine the diagnostic values of DNMT3B and ALYREF in breast cancer." (PMID 35812757, 2022). "For example, recent work has shown that miR-221 promotes the stemness of breast cancer cells by targeting DNMT3b, and the exosomal transfer of stroma-derived miR21 confers chemoresistance in ovarian cancer cells through targeting APAF1." (PMID 35681792, 2022). "This group also reported several miRNAs such as miR-26b, miR-29c and miR-148b regulated the expression of DNMT3B in multiple breast cancer cells." (PMID 35620052, 2022). "For example, the upregulation of DNMTs, such as DNMT1, DNMT3A, and DNMT3B, is correlated with endocrine therapy resistance in ER+ breast cancer." (PMID 35453496, 2022). "It has been reported that GNB4 was identified as a potential target silenced by DNA methylation via DNA methyltransferase 3B (DNMT3B), which can promote the growth of breast cancer cells." (PMID 36479252, 2022). "Demethylation agent 5-aza-dc, an inhibitor of DNMT3A and DNMT3B, increased the expression of caspase 8 and maspin in breast cancer cell lines." (PMID 35620052, 2022). "Another study reported that DNMT3B was highly expressed and predicted reduced survival in breast cancer patients." (PMID 35620052, 2022). "This review will provide reference for further studies on the biological functions and molecular mechanisms of DNMT3A and DNMT3B in breast cancer." (PMID 35620052, 2022). "Increased DNMT transcript expression, including DNMT1, DNMT3a, and DNMT3b, in breast cancer tissues, suggests that DNMTs are involved in breast carcinogenesis." (PMID 35327559, 2022). "Cadherin 1 (CDH1), CDKN2A, the runt‐related transcription factor 3 (RUNX3), BRCA1 and RASSF1A are reported to be suppressed by DNMT3B‐dependent DNA hypermethylation in gastric or breast cancers." (PMID 34133843, 2022). "Intriguingly, only breast cancer patients with higher expression of DNMT3B and ALYREF had poorer OS and RFS." (PMID 35812757, 2022). "In conclusion, DNMT3A and DNMT3B play an enormously critical role in the occurrence and development of breast cancer." (PMID 35620052, 2022). "Another group showed that microRNA-29b (miR-29b) can bind with 3′-UTR of DNMT3A and DNMT3B and inhibit the mRNA level of DNMT3A and DNMT3B, leading to multiple gene promoter methylation in breast cancer cells and suppression of cell proliferation." (PMID 35620052, 2022). "Multiple signaling pathways are validated to govern DNA methylation in breast cancer and some of these pathways are related to DNMT3a/DNMT3b." (PMID 35620052, 2022). "In keeping with this finding, another investigation also confirmed miR-221 maintained CSCs via suppressing DNMT3B and increasing the expression of stemness genes in breast cancer, such as Nanog and Oct3/4 genes." (PMID 35620052, 2022). "Unsurprisingly, there is prior evidence to suggest that DNMT3B affects the progression of breast cancer by targeting the STAT1/FOXO1 pathway." (PMID 36061358, 2022). "MiR-221 is another miRNA involved in DNMT3b targeting, which can elevate the cancer stem cell properties such as Oct3/4 and Nanog through downregulation of DNMT3b in breast cancer cell lines." (PMID 33632341, 2021).
breast carcinoma (continued). "In another study, the expression of DNMT1, DNMT3A, and DNMT3B in 256 breast cancer and 36 breast fibroadenoma cases were investigated." (PMID 33498667, 2021). "In the present study, we therefore investigated epigenetic marks and the interaction of DNMT3B with DNA at enhancer regions in response to PTS in breast cancer cells." (PMID 34439480, 2021). "In the CUL4A (component of cullin-ring-based E3 ubiquitin protein ligase complex) over expressing tissues such as hepatomas and breast cancer DNMT3B activity was enhanced due to its interaction with CUL4A-NEDD8 resulting in hypermethylation." (PMID 33604794, 2021). "The expression of miR-29a and miR-29b were found to target DNMT3A and DNMT3B in in vitro and in vivo models of breast cancer." (PMID 33604794, 2021). "Knock down and re-expression of miRNAs showed that miR-26b, miR-29a, miR-29b, miR-29c and miR-148b down regulate DNMT3B in breast cancer cells." (PMID 33604794, 2021). "Approximately, 30% of breast cancer patients showed overexpression of DNMT3B and 3–5% showed overexpression of DNMT1 and DNMT3A." (PMID 33604794, 2021). "A further study showed that combination of sulforaphane and withaferin A, another natural compound, significantly causes down-regulation of overexpressed DNMT3a, DNMT3b, and HDAC1 and breast cancer cell death." (PMID 32903500, 2020). "To establish the potential roles of the various DNMTs in mediating FOXO3a promoter methylation in breast cancer, we knocked down DNMT1, DNMT3A, and DNMT3B in breast cancer cells using specific small interfering RNAs (siRNAs)." (PMID 31296961, 2020). "It is noted that DNMT1, DNMT3a, and DNMT3b are all recruited to the FOXO3 promoter in breast cancer HCC70 and MDA-MB-468 cells." (PMID 31296961, 2020). "The anticancer effects of sulforaphane were found to be mediated by a global DNA hypomethylation, decreased levels of DNMT1 and DNMT3b and changes in the microRNA profiles of the three breast cancer cells lines." (PMID 32903500, 2020). "The re-expression of these miRNAs reduces the levels of DNMT3B mRNA in hypermethylated breast cancer cell lines." (PMID 33198240, 2020). "Several miRNAs, including miR-26a, miR-26b, miR-26c, miR-203, and miR-222 regulate DNMT3B mRNA in breast cancer cell lines and Burkitt lymphoma." (PMID 33198240, 2020). "Ralhan and co-workers showed that genistein is able to induce a significant decrease in the transcript levels of all the DNMTs including DNMT1, DNMT3a, and DNMT3b, in breast cancer." (PMID 32903500, 2020). "By targeting DNMT3b, miR-221 became involved in tumorigenicity through regulating the stemness of breast cancer cells." (PMID 32010179, 2019). "All together, these results suggest that miR-29c inhibits breast cancer by targeting the DNMT3B/TIMP3/STAT1/FOXO1 pathway." (PMID 29796115, 2018). "The binding of miR-29c to the 3′UTR of DNMT3B was examined, and the effects of knockdown of DNMT3B on proliferation, migration, and invasion were investigated in breast cancer cell lines." (PMID 29796115, 2018). "Consistent with human cell line data, Ets1 expression was negatively correlated with Dnmt3a and Dnmt3b in normal specimens, while Ets1 level is positively correlated with Apobec3c in human breast cancer specimens." (PMID 30467308, 2018). "Western blot and immunochemistry were used to examine the expression of DNA methyltransferase 3B (DNMT3B) protein in breast cancer cells and tissues." (PMID 29796115, 2018). "Tollefsbol and coworkers reported that 15 μM RVT was able to decrease DNMT enzymatic activity and mRNA levels of DNMT1, DNMT3A and DNMT3B in HCC1806 breast cancer cells." (PMID 29104258, 2017). "Forty eight percent of patients were classified as hypomethylated, about 38% as methylated and 14% as hypermethylated, suggesting that DNMT3B promoter in breast cancer patients tends to be hypomethylated." (PMID 28979331, 2017).
breast carcinoma (continued). "In vivo studies also demonstrated that RVT (25 mg/kg/day) decreases DNMT3b expression in a rodent model of estrogen-dependent mammary carcinoma." (PMID 29104258, 2017). "To address the possibility that the H19/SAHH/DNMT3B pathway mediates metformin effects in other cancer cells, we tested the effects of metformin on the human breast cancer-derived cell line MCF-7." (PMID 27775072, 2017). "In the present study we attempted to knockdown the expression of DNMT3B at the transcriptional level, via siRNA mediated promoter methylation in the breast cancer cell line, MDA-MB-453." (PMID 28979331, 2017). "In our previous study we also showed that DNMT3B promoter in breast cancer patients tends to be hypomethylated." (PMID 28979331, 2017). "In the present study, we demonstrate that DNMT3b represses the expression of Nanog and Oct 3/4 and increases the number of breast cancer cell spheres." (PMID 26556862, 2016). "Our results strongly confirm that ERα can activate DNMT1 and DNMT3b genes by direct binding to the gene promoters in breast cancer cells." (PMID 26980709, 2016). "It deserves further investigating with more breast cancer cell lines and tissue samples, since DNMT3b expression is shown to be negatively correlated with RFS and DMFS of ERα-positive breast cancer patients by the Kaplan-Meier Plotter analysis." (PMID 26980709, 2016). "The high expression of DNMT3B we report is consistent with the described hypermethylator phenotype of this breast cancer subtype and itself has prognostic value." (PMID 27863398, 2016). "Among these enzymes, over-expression of Dnmt3b have been found in the tumor tissues of approximately 30% of breast cancer patients, whereas Dnmt1 and Dnmt3b are over-expressed in approximately 5% and 3% of breast tumors." (PMID 25928539, 2015). "Of note, miR-29c is itself a post-transcriptional regulator of DNMT3b, and others have shown that DNMT3b is overexpressed in breast cancer cell lines with a hypermethylator phenotype." (PMID 26539832, 2015). "DNA methyltransferase-3b (DNMT3b) is a de novo methyltransferase and is over expressed in variety of tumors, such as lung cancer, breast carcinomas, hepatocellular carcinoma and large B-cell lymphomas." (PMID 26262893, 2015). "The expression of several DNA methyl transferases (DNMT1, DNMT3a, and DNMT3b) has been found to be elevated in breast cancer tissue." (PMID 26694341, 2015). "DNMT3b is overexpressed in 30% of breast cancers and treatment with AZA has been found to return DNMT3b expression to normal levels in a breast cancer rat model." (PMID 25647662, 2015). "In breast cancer, ~30% of patients revealed overexpression of DNMT3b in the tumor tissue as compared to normal breast tissue." (PMID 24822169, 2014). "In this study, we investigated possible molecular mechanisms governing DNMT3b overexpression driving aberrant DNA hypermethylation, with a focus on miR-mediated regulation of DNMT3b in basal-like breast cancers." (PMID 24297604, 2014). "Other studies show that zebularine decreases levels of DNMT1, DNMT3a, and DNMT3b in breast cancer cell lines as well as DNMT1 and partially DNMT3b in bladder cancer cells." (PMID 26161298, 2014). "Several studies in the literature have shown that DNMT3b is often overexpressed in different types of cancers including breast cancer." (PMID 24297604, 2014). "This fundamental observation related to the basal-like breast cancers underscores the significance of understanding the mechanism contributing to the overexpression of DNMT3b in these deadly breast cancers." (PMID 24297604, 2014). "The objective of the current study was to determine the role of microRNA dysregulation in the molecular mechanism governing DNMT3b overexpression in primary breast cancers that express aberrant DNA hypermethylation." (PMID 24297604, 2014).
breast carcinoma (continued). "While the expression of the DNMT3b-related aberrant DNA hypermethylation among basal-like breast cancers is now well established, the molecular mechanism governing the hyper methylation defect has not been examined in primary breast cancer." (PMID 24297604, 2014). "The level of DNMT3B protein is significantly elevated in hypermethylated human breast cancer cell lines, leading to an increased DNMT activity and high rates of methylation-dependent gene silencing." (PMID 23638630, 2013). "In the present study, our goal was to elucidate the molecular mechanism accounting for overexpression of DNMT3b in hypermethylator breast cancer cell lines." (PMID 22664488, 2012). "We identified a novel hypermethylation defect that is expressed in a subset of breast cancer cell lines and is characterized by epigenetic silencing of methylation-sensitive genes secondary to overexpression of DNMT3b and DNA methyltransferase hyperactivity." (PMID 22664488, 2012). "Our observations suggest strongly that the DNA methylation machinery (and specifically DNMT3b) represents new/novel molecular target for development of drugs and treatment strategies for basal-like breast cancer." (PMID 22664488, 2012). "A subset of clinical samples of breast cancer was characterized by high methylation levels, which coincided with increased DNMT3B expression." (PMID 20830311, 2010). "The results of the current study suggest that the mechanism that accounts for the hypermethylator phenotype in human breast cancer cell lines is elevated DNMT activity secondary to overexpression of DNMT3b." (PMID 18221536, 2008). "Finally, this approach also highlighted a number of potential tumour suppressor genes that are inactivated by ectopic DNMT3B expression, and thus provided a novel insight into epigenetically driven aggressive breast cancers." (PMID 40585280, 2025). "Following an original approach based on the identification of off-context tissue-specific gene activation in breast cancer, we recently identified the de novo DNA methyltransferase DNMT3B, along with four other genes, as markers of highly aggressive breast cancer subtypes." (PMID 40585280, 2025). "In this manner, the regulatory loop involving TGF-β1/miR-200s/miR-221/DNMT3B plays a crucial role in sustaining the phenotypic characteristics of CAFs and is indispensable for their functional involvement in facilitating the progression of breast cancer." (PMID 37705098, 2023). "For example, we found that an alternative transcript isoform of DNMT3B, lacking two exons that encode part of its C-terminal catalytic domain, is highly enriched in basal B breast cancer cell lines." (PMID 37553321, 2023). "We also highlighted that targeting DNMT3A and DNMT3B could be useful for anti-breast cancer treatment." (PMID 35620052, 2022). "The hypermethylation in the CXCL12 promoter region in more than 50% of breast tumors was detected by methylation-specific PCR, and the expressions of DNMT1 and DNMT3b were distinctly higher in CXCL12-methylated breast cancers than in CXCL12-unmethylated breast cancers." (PMID 35770088, 2022). "DNMT3B is known to influence breast cancer development via regulation of the STAT1/FOXO1 pathway." (PMID 36061358, 2022). "One report showed that DNMT3B might service an accessory DNA methyltransferase to inhibit the expression of CXCL12 in MCF-7 breast cancer cells." (PMID 35620052, 2022). "Through the H19/SAHH/DNMT3B axis, H19 may induce autophagy activation, which may help to produce tamoxifen resistance in breast cancer." (PMID 35813295, 2022). "Approximately 30% of all ER+ breast cancer cases exhibit upregulated expression of DNMT3B." (PMID 35453496, 2022). "DNMT1, DNMT3A and DNMT3B increased the DNA methylation of FOXF2 in breast cancer cells." (PMID 35620052, 2022). "In addition, MUC1-C induces the expression of DNMT1 and DNMT3b in breast cancer and induces the DNA methylation of CDH1 tumor suppressor gene and the induction of E-cadherin expression." (PMID 35978806, 2022).
breast carcinoma (continued). "Clearly, numerous miRNAs regulate the expression of DNMT3A and DNMT3B in breast cancer." (PMID 35620052, 2022). "This study suggested that miR-29b could regulate DNMT3A and DNMT3B and suppress proliferation of breast cancer cells." (PMID 35620052, 2022). "By an array-based DNA methylation profiling, breast cancer patients with high methylation levels and upregulation of DNMT3B could have poor prognosis." (PMID 35620052, 2022). "Hence, targeting IL-6 or PGE2 reduced DNMT3B induction and enhanced the efficacy of programmed cell death protein 1 (PD-1) immunotherapy in preclinical mouse models of breast cancer metastasis." (PMID 35267528, 2022). "Moreover, expression correlation analysis suggested that DNMT3B was markedly positively associated with VEGFA and EZH2 in breast cancer." (PMID 35812757, 2022). "Conclusively, VEGFA and EZH2 may be the most potential targets in the DNMT3B-related miRNA–mRNA network in breast cancer." (PMID 35812757, 2022). "To understand a possible functional role of DNMT3B in mediating epigenetic effects of stilbenoid polyphenols, we performed ChIP for DNMT3B in invasive MCF10CA1a breast cancer cells upon 9-day treatment with PTS at 7 μM concentration, followed by next-generation sequencing." (PMID 34439480, 2021). "Furthermore, the survival analysis revealed that increased levels of DNMT3B significantly correlated with the decreased overall survival rate (p < 0.01) in breast cancer patients." (PMID 33604794, 2021). "Furthermore, it was identified that miR-221-3p intensifies cancer stemness by targeting DNA methyltransferase-3 beta (DNMT3B) in breast cancer." (PMID 33799952, 2021). "This may be important clinically, with lower expression levels of miR-29c, miR-148a, miR-148b, miR-26a, miR-26b, and miR-203 demonstrated to contribute to DNMT3b overexpression in hypermethylated breast cancer cell lines (Hs578T, HCC1937 and SUM185)." (PMID 33050637, 2020). "In breast carcinoma, chronic intermittent exposure to adriamycin induced hypermethylation that was associated with multidrug resistant phenotype in correlation to an upregulation of DNMT1, DNMT3A and DNMT3B and an increase in DNA methyltransferase activity." (PMID 31022903, 2019). "Our findings demonstrate that H19 induces autophagy activation via the H19/SAHH/DNMT3B axis, which could contribute to tamoxifen resistance in breast cancer." (PMID 31340867, 2019). "However, the involvement of DNMT3b in resveratrol activity was also identified in a genome-wide DNA methylation study in breast cancer cells." (PMID 30781847, 2019). "To address which methyltransferases are responsible for DNA methylation at CpG sites and non-CpGs within the first exon of the HIF-1α gene, we detected the endogenous expression levels and patterns of DNMT3a and DNMT3b in various breast cancer cell lines by western blot." (PMID 30940798, 2019). "In addition, miR-29c was found to bind 3′UTR of DNMT3B and inhibits the expression of DNMT3B, which was elevated in breast cancers." (PMID 29796115, 2018). "Knockdown of DNMT3B reduced the proliferation, migration, and invasion of breast cancer cell lines." (PMID 29796115, 2018). "In addition, the direct binding of miR-29c to the wild-type 3′UTR of DNTM3B indicates that miR-29c is the direct post-transcriptional regulator of DNMT3B, which is elevated in breast cancer and methylates the promoter of the TIMP3 gene." (PMID 29796115, 2018). "We showed here that GNB4 was downregulated in both fulvestrant- and tamoxifen-resistant breast cancer cell lines, and that this was attributed to DNMT3B-mediated DNA methylation, because knockdown of DNMT3B by siRNA significantly elevated the expression of GNB4 at both mRNA and protein levels." (PMID 30103729, 2018). "In breast cancers, DNMT3B was also post-transcriptionally regulated by miRNAs." (PMID 29796115, 2018).